INS (insulin)
Diseases named in the same sentence as INS in open-access papers (continued):
Sharing a sentence is not in itself a finding about the gene and the disease.
type 1 diabetes (continued). "Type 1 diabetes is commonly preceded by seroconversion to one or multiple islet autoantibodies, including insulin autoantibodies (IAAs), glutamic acid decarboxylase autoantibodies (GADAs), insulinoma-like 2 autoantibodies (IA-2As), and zinc transporter 8 autoantibodies (ZnT8As)." (PMID 40994736, 2025). "Adults with type 1 diabetes (T1D) who fast during Ramadan remain a severely understudied population in terms of changes in glycemic control, making evidence-based recommendations for insulin adjustments difficult in this age-group." (PMID 40510485, 2025). "As a consequence of these learnings and as suggested in the recent guidelines from the International Society for Pediatric and Adolescent Diabetes, a century after the first clinical use of insulin, there is an urgent need to change the paradigm of diagnosis and therapy of type 1 diabetes." (PMID 39753267, 2025). "Moreover, after a decades-long lull following the discovery of insulin over a century ago, multiple therapeutic milestones have been reached in medical efforts to preserve beta cell function and delay the onset of type 1 diabetes." (PMID 41226824, 2025). "Known triggers of DKA include new onset of type 1 diabetes, insulin cessation, infection, and non-infectious causes such as acute myocardial infarction, alcohol, and pancreatitis." (PMID 40546498, 2025). "Type 1 diabetes (T1D) is an autoimmune disease defined by the destruction of insulin-producing β cells of the pancreas, resulting in dysglycemia and lifelong dependence on exogenous insulin." (PMID 40149868, 2025). "Type 1 diabetes is a metabolic syndrome caused by an imbalance of glucose, lipid and proteins, due to a lack of insulin synthesis by β-cells, or the production of insufficient insulin for the regulation of intermediate metabolism." (PMID 39861427, 2025). "This pilot study provides promising preliminary evidence that encapsulated autologous fecal microbiota capsules could be a feasible and safe adjunct therapy to preserve endogenous insulin production in type 1 diabetes." (PMID 41226824, 2025). "However, the DIDS scale is a short and easy-to-administer tool that is adequate for use across all insulin delivery devices, and has shown robust psychometric properties in individuals with type 1 diabetes." (PMID 39387915, 2025). "In type 1 diabetes, the role of lymphocytes is more direct: cytotoxic CD8+ T lymphocytes and other immune cells are activated, specifically recognizing and attacking pancreatic β cells that secrete insulin, resulting in absolute insulin deficiency." (PMID 41384020, 2025). "Type 1 diabetes (T1D) is a chronic autoimmune disorder characterized by the targeted destruction of insulin-producing pancreatic β-cells, resulting in insulin deficiency and the requirement for lifelong exogenous insulin therapy to regulate blood glucose levels." (PMID 40362176, 2025). "Type-1 diabetes patients require life-long insulin replacement therapy." (PMID 41514592, 2025). "Therefore, the aim of this meta-analysis it to systematically summarize the evidence on adding DPP-4 inhibitors to insulin therapy in patients with type 1 diabetes." (PMID 41026724, 2025). "Since glucose metabolism has been shown to be altered by serum CN1 concentrations in obese subjects, we now assessed whether insulin sensitivity and glucose variability are associated with serum CN1 in type-1 diabetes cohort with CGM." (PMID 40002779, 2025). "It has also been suggested that vitamin D may protect β cells and improve insulin sensitivity, and epidemiological studies have suggested a correlation with type 1 diabetes incidence." (PMID 39796229, 2025). "Our results suggest impairments in metabolic flexibility that in the setting of persons with long‐standing type 1 diabetes may be due to insulin resistance and poor glucose availability during intense exercise." (PMID 41392490, 2025).
type 1 diabetes (continued). "However, few studies have evaluated insulin secretion and glucagon or cortisol levels in relation to NH in patients with insulin-dependent diabetes by using CGM." (PMID 40932945, 2025). "The incidence of type 1 diabetes, defined by diabetic ketoacidosis at presentation or the requirement of insulin therapy within 12 months of diagnosis, is low in Chinese youth, with rates reported at five to six per 100,000 person‐year in a territory‐wide cohort in Hong Kong." (PMID 40966384, 2025). "This approach aligns with the goal of minimizing exogenous insulin use and offers a non-pharmacological option to address cardiovascular risk in type 1 diabetes." (PMID 40045281, 2025). "Type 1 diabetes (T1D) which is caused by the autoimmune destruction of beta pancreatic cells resulting in lack of insulin production." (PMID 39792250, 2025). "To achieve this, we performed a randomized, controlled, crossover study to examine the impact of adding teleconsultation and digital data support to CGM use on glycemic control in children and adolescents with type 1 diabetes taking multiple daily injections (MDIs) of insulin." (PMID 41049863, 2025). "In addition to insulin being the primary treatment for type 1 diabetes, significant progress has been made in developing interventions to delay its onset." (PMID 40735262, 2025). "Detection of enterovirus RNA was significantly more frequent in single islet autoantibody-positive donors compared with donors with type 1 diabetes with insulin-deficient islets (p<0.001) and control (non-diabetic) donors (p=0.004)." (PMID 40095061, 2025). "Particularly in the treatment of type 1 diabetes, blood glucose fluctuations are large due to severe reduction in endogenous insulin secretion, and managing the disease necessitates treatment with frequent insulin injections or continuous subcutaneous insulin infusion." (PMID 40382628, 2025). "A similar mechanism may be at play in the death of insulin-producing cells in type 1 diabetes, where inflammation and elevated glucose levels lead to severe beta-cell stress." (PMID 41361288, 2025). "Autoantibody screening is useful in suspected cases, with common markers including thyroid peroxidase antibodies for autoimmune thyroid disease, anti-IA2 and anti-insulin antibodies for type 1 diabetes, and 21-hydroxylase antibodies for autoimmune Addison’s disease." (PMID 40951041, 2025). "The role of insulin clearance in type 1 diabetes progression remains largely unexplored." (PMID 39560746, 2025). "When stratified by type of diabetes, in pregnant people with type 1 diabetes, those with a ≥15% insulin drop had a significantly lower BMI (24.3 vs. 26.9 kg/m2, p = 0.029) and were less likely to be nulliparous (25.0% vs. 49.1%, p = 0.019), with no other significant differences." (PMID 41227133, 2025). "Finally, according to the age of the participants of our cohort study, adolescents, especially those with type 1 diabetes, experience significant hormonal fluctuations during puberty, impacting insulin sensitivity and metabolic responses." (PMID 38954647, 2025). "However, specifically in type 1 diabetes, death before getting access to insulin probably also contributes to the low recorded incidence." (PMID 41023432, 2025). "Although Type 1 Diabetes is primarily driven by immune destruction of β-cells, the “honeymoon phase”, where symptoms temporarily improve upon insulin treatment, may involve some component of glutoxicity reversal." (PMID 38895272, 2025). "A previous study had shown non-insulin-dependent diabetes to be more prevalent at diagnosis in older adults, which complemented our findings by suggesting that the use of insulin might increase with growing disease duration among older adults." (PMID 41030747, 2025).
type 1 diabetes (continued). "The primary finding was that fenofibrate (160 mg/day) was well tolerated but did not influence beta cell function in adults and adolescents with newly diagnosed type 1 diabetes, as indicated by unchanged C-peptide secretion, insulin usage and glycaemic control." (PMID 39477880, 2025). "Typical fulminant type 1 diabetes shows irreversible insulin depletion after onset." (PMID 40406776, 2025). "The current study was designed to evaluate glycemic control and PROMs in a cohort of adult patients with type 1 diabetes using different treatment modalities, including traditional strategies for glucose monitoring and insulin administration and more advanced technological approaches." (PMID 39387915, 2025). "Furthermore, the genetic risk associated with INS genotype and PRS also diminishes with age, making age a critical factor in modifying genetic susceptibility to early‐stage type 1 diabetes." (PMID 40134221, 2025). "Hybrid closed-loop systems, through their glucose-responsive insulin delivery, improve glycaemic outcomes, increasing time in range without increasing the risk of hypoglycaemia in people with type 1 diabetes." (PMID 39146468, 2025). "Type 1 diabetes (T1D) management primarily relies on insulin therapy." (PMID 40347422, 2025). "To test this hypothesis, we conducted a single-blinded, random-order crossover study comparing the effects of a one-week RCD to an isocaloric, standard carbohydrate diet (SCD) on insulin sensitivity and endothelial function in adults with type 1 diabetes." (PMID 40045281, 2025). "Type 1 diabetes onset occurs at any time during childhood, but the incidence peaks during puberty, when rapid physical growth and substantial hormonal dynamics increase insulin resistance and demand." (PMID 39694913, 2025). "Increased resource utilization was associated with higher ASA classification, underweight BMI, use of general anesthesia, and comorbidities like insulin and non-insulin-dependent diabetes, COPD, CHF, hypertension, dialysis, steroid use, bleeding disorders, and SIRS." (PMID 40519386, 2025). "A study also revealed a higher rate of miscarriage among women with type 1 diabetes treated with continuous subcutaneous insulin infusion, suggesting that disease severity and insulin delivery modality may influence outcomes." (PMID 40944103, 2025). "By inhibiting neuroinflammation, insulin can contribute to neuronal survival, therefore, we aimed to investigate the presence of insulin in myenteric neurons and their nitrergic population in acute and chronic rat models of type 1 diabetes." (PMID 40497986, 2025). "For individuals with type 1 diabetes, insulin remains the first-line treatment." (PMID 40900896, 2025). "However, it has been generally accepted that T1D refers to immune-mediated diabetes and results from the destruction of the insulin-secreting β-cells of the islets of Langerhans in the pancreas." (PMID 40244115, 2025). "The aim of this study is to assess endothelial progenitor cells (EPCs) and circulating endothelial cells (CECs) at the time of type 1 diabetes (T1D) recognition concerning patients’ clinical state, remaining insulin secretion, and further partial remission (PR) occurrence." (PMID 40710348, 2025). "It most commonly occurs in patients with type 1 diabetes due to reduced insulin secretion." (PMID 39913488, 2025). "Type 1 diabetes is caused by an autoimmune response that destroys the insulin-producing beta cells in the pancreas, resulting in an absolute lack of insulin." (PMID 41280964, 2025). "Most participants had Type 1 diabetes and managed it with multiple daily insulin injections." (PMID 40181799, 2025). "Euglycemic diabetic ketoacidosis (euDKA), a rare but serious complication, has been primarily reported in patients with type 1 diabetes and may be precipitated by acute illnesses, inappropriate insulin dose reductions, or omissions." (PMID 40692593, 2025).
type 1 diabetes (continued). "It primarily exists in two major forms: type 1 diabetes (T1D), an autoimmune condition leading to the destruction of pancreatic β-cells, which are responsible for the production and secretion of insulin; and type 2 diabetes (T2D), which involves insulin resistance and progressive β-cell dysfunction." (PMID 40871679, 2025). "It has also been shown that NO mediates insulin secretory dysfunction in type 1 diabetes." (PMID 38864887, 2024). "Insulin replacement therapy has been available to treat type 1 diabetes for 100 years, with the last 30 years witnessing the development of more efficacious insulins, more accurate insulin delivering methods and more sophisticated ways to monitor blood glucose." (PMID 38353727, 2024). "At 27 weeks of gestation, a 23-year-old white gravida 2 para 0, with a type 1 diabetes (first diagnosis 8 years ago, HbA1c periconceptual 6%) on intensified insulin regimen was transferred to our hospital from a peripheral clinic because of persisting hematemesis, presenting in a desolate condition." (PMID 38958733, 2024). "In conclusion, although insulin is still the main form of treatment for type 1 diabetic patients, our study shows that the treatment with insulin alone for 30 days is not able to prevent all the cardiac and autonomic alterations due to hyperglycemic state in STZ-induced diabetic rats." (PMID 38794147, 2024). "Hence, people with type 1 diabetes depend on exogenous insulin to survive and control their blood glucose." (PMID 38920672, 2024). "In summary, the engineered Insulin-MHC-Fc complex represents a tailored immunotherapeutic agent capable of utilizing patients’ endogenous immune cells to achieve antigen-specific clearance of autoreactive T cells in type 1 diabetes." (PMID 38097717, 2024). "Type 1 diabetes is a chronic autoimmune disease that causes the pancreas to produce very little or no insulin." (PMID 39300612, 2024). "People with type 1 diabetes (T1D) need insulin for survival." (PMID 39468682, 2024). "The impacts of insulin degludec U100 (Deg‐100) and insulin glargine U300 (Gla‐300) on glycemic variability (GV) in patients with type 1 diabetes, as well as the impact of major nutrient components on GV in these patients, remain unclear." (PMID 39588847, 2024). "Type 1 diabetes (T1DM) accounting ~10% of diabetic patients, is characterized by a selective autoimmune destruction of pancreatic β-cells leading to nearly complete loss of insulin production that typically develops over several years." (PMID 38966213, 2024). "Type 1 diabetes, a disorder identified as diabetic ketoacidosis may happen during severe insulin lack." (PMID 38371502, 2024). "The strong correlation between GMI and A1c suggests a potential role for telemedicine in type 1 diabetes management as insulin adjustments could be conducted using TIR, GMI, and CGM mean glucose information as clinical guides." (PMID 38745900, 2024). "A cohort study revealed that type 1 diabetes affects adiposity and skeletal muscle insulin sensitivity more strongly in women than in men, which may contribute to the relatively higher cardiovascular risk among women." (PMID 38750553, 2024). "Additionally, it has been demonstrated that administering IGF-I to adults with type 1 diabetes improves insulin sensitivity by elevating systemic IGF-I levels." (PMID 38468961, 2024). "T1D, also known as insulin-dependent diabetes, is caused by the destruction of β cells in the pancreas, resulting in an absolute lack of insulin, and is mainly seen in children and adolescents." (PMID 39777226, 2024). "Patients with type 1 diabetes are more likely to experience hypoglycaemic episodes compared to type 2 diabetics, although equivalent rates are seen in type 2 diabetics on long-term insulin therapy." (PMID 38392992, 2024). "We performed a longitudinal analysis to determine whether insulin resistance or insulin sensitivity had a role in the transitioning between pre-symptomatic stages of type 1 diabetes development." (PMID 37914981, 2024).
type 1 diabetes (continued). "Along with insulin therapy, glycemic self-monitoring plays an important role in type 1 diabetes." (PMID 39376804, 2024). "However, the data about the comparison between these two insulin analogs in type 1 diabetes is limited." (PMID 38541176, 2024). "This could be attributable to a more pronounced decline in insulin sensitivity during puberty in young women with type 1 diabetes." (PMID 39595717, 2024). "In another Italian study, eleven adults with type 1 diabetes on an insulin pump underwent a week-long study with a randomized cross-over design, alternatively adding monounsaturated fat (extra-virgin olive oil), saturated fat (butter), or a low-fat diet to meals." (PMID 39519472, 2024). "This case suggests that montelukast may reduce insulin needs in type 1 diabetes patients, potentially through its anti-inflammatory effects on eosinophils." (PMID 39749265, 2024). "In contrast, insulin has remained the main approved treatment for Type 1 Diabetes (T1D)." (PMID 39429740, 2024). "According to our findings, maternal microchimeric cells have been related to Type 1 diabetes either acting against the offspring pancreatic β-cell, producing insulin, differentiating into endocrine and exocrine cells, or simply being indicators of tissue damage." (PMID 39336498, 2024). "The insight gained from ADAPT study, combined with that from previously published studies of other automated insulin delivery systems, suggests that AHCL should be considered at the early stages in the type 1 diabetes treatment pathway, in order to have reduced risk of long-term complications." (PMID 39004734, 2024). "In addition, there is a study in which rabbit islets were successfully used as a source of insulin in the xenotransplantation of microcapsules into patients with type 1 diabetes." (PMID 39408998, 2024). "Type 1 Diabetes (T1D) is driven by dysregulated islet autoantigen-specific B and T lymphocytes that escape control of immune tolerance mechanisms and mediate damage of insulin-producing beta cells in pancreatic islets." (PMID 38515750, 2024). "Among type 1 diabetes patients receiving insulin treatment, a higher percentage of patients in the sotagliflozin group achieved glycated hemoglobin levels below 7.0%, with no occurrence of severe hypoglycemia or diabetic ketoacidosis, compared to the placebo group." (PMID 38694909, 2024). "Type I diabetes patients are insulin-dependent and mostly affect from 4 to 7 and 10 to 14 years." (PMID 38355744, 2024). "Type 1 diabetes mellitus (T1DM) is a metabolic disorders caused by autoimmunity leading to a lack of insulin secretion from pancreatic beta cells." (PMID 39027096, 2024). "However, after 17 cycles, he developed a treatment related adverse event (TRAE) of pancreatic endocrine dysfunction, leading to type 1 diabetes, managed with subcutaneous insulin injections." (PMID 39247185, 2024). "T1DM, (a.k.a., juvenile diabetes or insulin-dependent diabetes), is an autoimmune disorder whereby the body views its insulin-producing pancreatic beta (β) cells as a foreign threat, and subsequently, directs the immune system to attack and destroy them, leading to insulin insufficiency." (PMID 38444587, 2024). "First, insulin icodec is yet to be investigated in type I diabetes." (PMID 38213906, 2024). "A study in Sudan revealed that vitamin D deficiency was prevalent among type 1 diabetes patients, and supplementation led to a significant decrease in fasting blood glucose, though changes in HbA1c and insulin needs were not significant." (PMID 39457127, 2024). "However, the use of BB insulin therapies is recommended as the standard regimen for management or type 1 diabetes." (PMID 36896906, 2024). "In studies of human pancreata from patients with type 1 diabetes, the frequency of insulin/glucagon bihormonal islet cells was found to be higher than in non-diabetics, suggesting that a similar regenerative pathway might also exist." (PMID 39456933, 2024).